HIF1A (hypoxia inducible factor 1 subunit alpha)
Diseases named in the same sentence as HIF1A in open-access papers (continued):
Sharing a sentence is not in itself a finding about the gene and the disease.
tumor (continued). "Conversely, NQO1-knockdown tumours (RKO/pshNQO1) showed significantly less HIF-1α expression even in the pimonidazole-positive hypoxic areas." (PMID 27966538, 2016). "Tumours of pT1M1 stage showed a positive correlation between HIF-1α and phospho-S6RP S235/236 expression (r=0.51; Spearman's rank correlation coefficient)." (PMID 27291893, 2016). "Recent findings indicate mROS as crucial regulators of protein stabilization and transcription of HIF1A, one of the master regulators of tumor progression." (PMID 27138568, 2016). "miR-429, a tumor suppressor that down-regulates almost all genes in anaerobic glycolytic pathway (e.g. GLUTs) via the oncogenic TF HIF1α." (PMID 27358718, 2016). "Combination treatments of tumor xenografts with paclitaxel or gemcitabine in combination with the HIF-1α inhibitor digoxin proved more effective than either of the drugs tested as a single agent." (PMID 27066484, 2016). "HIF-1α induction occurred in parallel with a variety of tumour responses including EMT, metabolic reprogramming, chemoresistance and was strongly associated with increased peritoneal tumourigenicity in nude mice." (PMID 26967059, 2016). "In vivo studies demonstrated that metformin delayed tumor growth and attenuated the expression of HIF-1α in HCC tumor xenografts." (PMID 26621849, 2016). "The expression of HIF-1α was correlated with tumor characteristics, microvascular density (MVD) and survival." (PMID 26497365, 2016). "Large areas where HIF was stabilized were found mainly in the centre of B16 tumours, as revealed by immunocytochemistry using a HIF1α antibody." (PMID 27426915, 2016). "Branco-Price and colleagues showed that there was slower migration of tumour cells through HIF-1α deficient EC layers and reduced metastasis in HIF-1α deficient mice." (PMID 27275004, 2016). "Another possibility is that hypoxia truly boosts glycolytic rates in tumor-infiltrating T cells by stabilizing HIF1α; however, the available glucose in the tumor microenvironment is insufficient to support T cell anti-tumor responses." (PMID 26885366, 2016). "But there is no unified and effective method to evaluate the activity level of HIF-1α within the tumor cells." (PMID 26853843, 2016). "It is worth mentioning that tumor cells can exhibit augmented levels of HIF1α under normoxic conditions, a phenomenon known as pseudo-hypoxia." (PMID 28040803, 2016). "Adaptation of tumor cells to hypoxia is mainly regulated by HIF-1α, which has been reported to be upregulated in HCC." (PMID 26621849, 2016). "Analysis of WT and R132H IDH1 GBM xenografts revealed that R132H IDH1 tumours had low to barely detectable nuclear HIF1α (and TNC) despite evident necrosis (asterisks) and hypoxia." (PMID 27820599, 2016). "CSCs have been considered to be dependent on HIF-1a for survival and tumour growth under hypoxic condition." (PMID 27976736, 2016). "HIF-1α thus appear at the centerpiece of a signalling node by which tumor cells take control of their invasive behaviour according to their microenvironment and growth factor context." (PMID 26909598, 2016). "A possible explanation for the inconsistent pro- or anti-tumorigenic effects of HIF1α in some tumor types is that its function is highly dependent on the specific cellular context." (PMID 26743088, 2016). "Under hypoxic conditions, HIF1α tends to translocate into nuclei and activates the transcription of genes involved in essential cancer progressions including tumor metastasis and invasiveness." (PMID 27899819, 2016). "The YAF-treated tumor samples were analyzed by IHC for levels of HIF-1α/EMT related proteins HIF-1α, E-cd, Claudin-4, and VIM." (PMID 27806701, 2016). "We therefore explored gene expression alterations in tumor tissue in relation to high stromal HIF-1α protein expression." (PMID 27634881, 2016). "We found gene expression value of VEGFA and SLC2A1 in the tumor component to be significantly positively correlated to stromal HIF-1α." (PMID 27634881, 2016).
tumor (continued). "Salmonella suppressed the expression of VEGF in tumor and angiogenic signaling cascades induced by HIF-1α." (PMID 27175584, 2016). "Increased HIF-1α induced by hypoxia can commit the adaptive changes in gene expressions of tumor cells." (PMID 26822586, 2016). "In renal cell carcinoma, stabilization of HIF1α reduced tumor progression, while overexpression of HIF2α resulted in increased tumorigenesis." (PMID 27708247, 2016). "In contrast with HIF-2α, which is expressed in certain cell types of vertebrate species, the expression of HIF-1α is observed in most metazoan species and involved in the regulation of epithelial-mesenchymal transition of tumor." (PMID 27456341, 2016). "Overexpression of HIF-1α was found in 67 (73 %) of tumor tissues and in 11 (27 %) of the normal group." (PMID 26846782, 2016). "Attenuation of hCG expression by siRNA in OVCAR-3 cells suppressed the expression of endothelial cell markers and HIF-1α by tumour cells." (PMID 27346985, 2016). "A previous study from our laboratory demonstrated that hypoxia induces PD-L1 expression in tumor cells in a HIF-1α-dependent manner." (PMID 26859684, 2016). "Because of the HIF-1α is related with hypoxia, this index has been widely used in the assessment of tumor hypoxia condition." (PMID 26853843, 2016). "Higher level of stain for HIF1α was present in the tumor tissues, but ethanol appeared to reduce this stain." (PMID 26951793, 2016). "Although the intra-tumor concentration of doxorubicin in JC tumors is very low, such concentration was sufficient to increase HIF-1α and up-regulate Pgp levels, glycolytic genes levels, glucose uptake and metabolism through glycolysis and TCA cycle." (PMID 26980746, 2016). "We provide evidence that adipocytes drive metabolic reprogramming of tumor cells via oxygen-independent mechanism of HIF-1α activation that can be reversed by HIF-1α downregulation." (PMID 27588494, 2016). "HIF-1α K32A MT-expressing cells resulted in the increased tumour formation, weight and volume compared with the cells expressing HIF-1α WT." (PMID 26757928, 2016). "Currently, immunohistochemistry (IHC) is the main research method whichwas used in the evaluation of HIF-1α levels in tumor patients." (PMID 26853843, 2016). "The tumour hypoxic condition tends to promote molecular changes and eventually lead to the activation of HIF-1α." (PMID 27976736, 2016). "The role of HIF-1a has also been identified in promoting the recruitment of Treg cells to the tumor microenvironment via over-expression of cytokines and chemokines, such as TGF-β CCL28 by hypoxic tumor cells." (PMID 27066006, 2016). "Factors in the response of tumor cells to this distinct microenvironment are the activities of the hypoxia inducible factor-1α (HIF-1α), which is regulated in an oxygen-dependent manner." (PMID 27042656, 2016). "In this experiment, Cre+ mice had a 67% reduction in tumor growth compared with their HIF-1α Cre− littermates 14 days after tumor cell inoculation." (PMID 27834402, 2016). "The high expression levels of HIF-1α or HIF-2α have been correlated with worse tumor grade, venous invasion, intrahepatic metastasis, and capsule infiltration." (PMID 27094811, 2016). "The prognosis for tumor patients has been closely correlated with activation and expression level of HIF-1a which are regulated by many factors such as DEC2 (differentiated embryonic chondrocyte gene 2)." (PMID 27456341, 2016). "The mechanisms underlying the uptake of NIRF dyes in cancer cells have been previously reported to be increased by tumor hypoxia and activation of the HIF1α/OATPs signaling axis." (PMID 27329598, 2016). "This suggests that adipocyte-driven Warburg phenotype in tumor cells is likely a downstream effect of HIF-1α activation under normoxic conditions." (PMID 27588494, 2016). "Recently, HIF-1α has been shown to be essential for the maintenance of ‘tumour initiating’ or ‘cancer stem cells’ (CSCs) in various cancer types." (PMID 26967059, 2016).
tumor (continued). "We next investigated if diacetoxyscirpenol attenuates the angiogenic potential of cancer cells because HIF-1α plays a key role in tumor angiogenesis." (PMID 27613833, 2016). "Collectively, our in vitro and in vivo studies reveal for the first time that wogonin represses MM-stimulated angiogenesis and tumor progression via c-Myc/VHL/HIF-1α signaling axis." (PMID 26735336, 2016). "We found that MAOB levels correlated with tumor grade and hypoxia-inducible factor 1-alpha (HiF-1α) expression." (PMID 26689994, 2016). "The reason for chosen of A549 cells, which are known to express higher levels of more stable HIF-1α, which is important for tumor cells with limited oxygen supplies and it, is involved in proliferation and angiogenesis." (PMID 26867977, 2016). "In particular, HIF1α immunopositivity was found in both the cytoplasm and the nuclei of tumor cells and ECs, while in the peritumoral tissue the protein was mainly localized in the nucleus of ECs and in some cells with apparently normal morphology." (PMID 27705944, 2016). "An increased tumor volume, indicated by a higher T stage, will decrease the efficacy of oxygen diffusion in maintaining normoxia; hypoxic conditions and HIF-1α stabilization will occur in tumor cells that are located far from the distal end of the capillary." (PMID 27882053, 2016). "We have previously demonstrated that overexpression of HIF-1α is associated with advanced tumor stages in patients with PDAC and proposed that HIF-1α is an attractive target for the development of anticancer agents." (PMID 26872370, 2016). "Immunohistochemistry analysis showed an increase in the immunostaining intensity of HURP and the hypoxia-sensitive molecules, hypoxia-inducible factor 1-alpha (HIF-1α), VEGF, and heat-shock protein 60 (HSP60) in association with tumor grade." (PMID 27379206, 2016). "PHD inhibitors as fumarate/succinate produced by tumor cells during tricarboxylic acids cycle, is a potent way of HIF-1α stabilization." (PMID 27066006, 2016). "Overall, the expression of HIF-1α contributes to the progression of many solid tumors through the way of sustaining energy metabolism, maintaining biosynthesis and promoting tumor cell invasion and migration." (PMID 27606158, 2016). "HIF-1α is induced by hypoxia in solid tumors and enables tumor cell adaptation to low oxygen conditions." (PMID 27882053, 2016). "In contrast, R132H IDH1 GBM tumours expressing WT β1 integrin had low to negligible HIF1α and TNC protein expression, despite pronounced hypoxia." (PMID 27820599, 2016). "The xenograft tumor samples were then analyzed by IHC for levels of proteins such as HIF-1α, E-cd, Claudin-4, and VIM." (PMID 27806701, 2016). "Consistently, HIF-1α-knockdown almost completely inhibited tumour growth, even in the presence of overexpressed NQO1." (PMID 27966538, 2016). "We investigated expression patterns of HIF-1α in both the stromal and the epithelial tumor component in EC." (PMID 27634881, 2016). "In xenograft models, this fusion protein attenuates expression of HIF-1α target genes and reduces tumor growth." (PMID 27094811, 2016). "Expression of HIF-1α protein, HIF-1α mRNA, and miR-199a were determined in the epithelial cells of the tumor tissues." (PMID 26872370, 2016). "Subsequently, we performed triple immunofluorescent staining for SOX2, HIF-1α, and RNApII-S2P, and found a small number of tumor cells showing a SOX2+ HIF-1α+ RNApII-S2P-/low phenotype in the vicinity of necrotic areas." (PMID 26799577, 2016). "The identification of the key molecules involved in tumor hypoxia adaptation confirmed that CD147 up-regulation was mainly mediated by a combined effect of HIF-1α and specificity protein 1 (Sp1) on the activation of CD147 promoter." (PMID 27009812, 2016). "HIF-1α orchestrates downstream genes essential to the cells' adaption to hypoxia, and HIF-1α is an important transcription inducer for numerous growth factors and cytokines in tumor angiogenesis, most importantly VEGFA." (PMID 27634881, 2016).
tumor (continued). "In the present study we explore HIF-1α expression in EC in relation to preoperative functional imaging markers reflecting tumor microvasculature and metabolism, and find these parameters to be linked." (PMID 27634881, 2016). "Tumours with increased HIF-1α expression significantly correlated with HectH9 overexpression (P<0.001, X2 test)." (PMID 27934968, 2016). "This suggests that tumour growth is inhibited specifically through reduced NQO1-dependent HIF-1α expression." (PMID 27966538, 2016). "Its overexpression reduced HIF-1α levels, followed by tumor angiogenesis, growth, and metastasis suppression." (PMID 27551267, 2016). "Using clinical tumour samples, we confirmed that the HIF-1α/Daxx/Slug pathway is an outcome predictor." (PMID 28004751, 2016). "In tumor cells, succinate is demonstrated to stabilize HIF-1α protein by inhibiting proteasomal degradation." (PMID 28003810, 2016). "The HIF-1α suppression by diacetoxyscirpenol was confirmed by immunoblotting HIF-1α in tumor homogenates." (PMID 27613833, 2016). "PI3K is an important molecular signal transduction in tumor cells and an upstream signal pathway molecular of HIF-1α." (PMID 27042656, 2016). "Some investigators have shown that HIF-1α inhibits primary tumour growth, whereas HIF-2α enhances it60." (PMID 27358011, 2016). "In case 1, the expression of HIF-1α was detected in many of the perinecrotic tumor cells (staining: ++)." (PMID 27244880, 2016). "By employing the bioluminescence assay, we were able to demonstrate the suppression of HIF-1α transcriptional activation by pharmacologic inhibition of PIN1 in tumor hypoxia." (PMID 26784107, 2016). "Pro-inflammatory pathways are induced in tumor cells by oncogenic activation of transcription factors such as HIF-1α and NFκB, resulting in the high levels of inflammatory mediators detected in most solid tumors." (PMID 28066431, 2016). "In this study, we used the HIF-1α-based aptamer as the guide to specially monitor the tumour hypoxia and target cancer stem cells." (PMID 27976736, 2016). "Ectopic expression of these miRNAs reduces the expression of vascular endothelial growth factor (VEGF), a crucial transcriptional target of HIF1α, thereby decreasing angiogenesis, a process of blood vessel formation required for tumor growth and metastasis." (PMID 27358718, 2016). "The dye uptake is stimulated in part by tumor hypoxia and activated hypoxia-inducible factor 1α (HIF1α)/organic anion-transporting polypeptide (OATP) signaling." (PMID 27329598, 2016). "Recently, stable expression of HIF1α in tumor cells have been found even under normal oxygen tension that mediates immune adaptation through AKT/ERK and VEGFA axis." (PMID 26910842, 2016). "Since elevated HIF-1α participates in tumor progression, HIF-1α is considered as one of tumor markers and can be useful as a targeted candidate for anti-tumor therapeutics." (PMID 26822586, 2016). "As potent factors of tumor angiogenesis, HIF-1α and VEGF play important roles in the development, progression, and metastasis of HCC and are important for the efficacy evaluation of TACE of HCC patients and the development of individualized treatment regimens." (PMID 26985249, 2016). "One important consequence of hypoxia is the induction of HIF-1α-mediated accumulation of lipid droplets in tumor cells." (PMID 27588494, 2016). "Specifically, we demonstrate that tumor hypoxia can induce elevated expression of CCL28 through HIF1α." (PMID 27716621, 2016). "It was identified recently that hypoxia, through the action of HIF-1α, increases the expression of PD-L1 by tumor cells and by tumor-infiltrating MDSC." (PMID 27066484, 2016). "Increased hypoxia and glycolysis were further confirmed by the increased levels of HIF1α and HIF2α proteins in intermediate and angiogenic tumours and the presence of MCT4 in perinecrotic zones in the angiogenic phenotype." (PMID 27049916, 2016).
tumor (continued). "In conclusion, we found that diacetoxyscirpenol deregulates tumor adaptation to hypoxia by deregulating HIF-1α." (PMID 27613833, 2016). "Factors that are associated with pathological stress such as acute and chronic inflammation, infectious microorganisms, and tumor hypoxia stabilize HIF-1α protein." (PMID 27058421, 2016). "In order to adapt to the hypoxic condition, tumor cells up-regulate the expression of HIF-1α, which further aids tumor development and angiogenesis." (PMID 27271600, 2016). "To further study the changes in the tumor microenvironment hypoxia induced by antiangiogenic therapy, we examined the expression of HIF-1α in the tumor microenvironment in tumor tissue." (PMID 27703219, 2016). "One of the main contributions of HIF-1α to tumor promotion is the upregulation of angiogenic growth factors that provide oxygen to the hypoxic tumors." (PMID 26824423, 2016). "The immunofluorescence analysis of CA9 protein revealed a significant increase and typical membrane localization in 2D tumor cell cultures exposed to adipocytes, indicating activation of HIF-1α signaling." (PMID 27458427, 2016). "The ability of SIRT3 to suppress tumor growth via inhibiting reactive oxygen species(ROS) production and regulating HIF-1α stabilization of host cells has attracted considerable attention in recent years." (PMID 27483432, 2016). "pVHL silencing or inactivation will thus cause HIF-1α/2α accumulation, leading to vascular endothelial growth factor (VEGF) production and tumor angiogenesis." (PMID 27412013, 2016). "HIF-1α expression was confirmed in tumor tissues by immunohistochemistry of paraffin embedded tumors slides." (PMID 27708244, 2016). "Varying HIF-1α expression and β2-AR expression were observed between different histological differentiation and among the tumor node metastasis (TNM) stages (P < 0.05, respectively)." (PMID 26497365, 2016). "Correspondingly, with short exposure to proteasome inhibitor MG132 the increase in HIF1α occurred rapidly in CAFs relative to tumor cell lines." (PMID 27623078, 2016). "In tumor cells, ATP production was impaired and HIF-1α-dependent genes were upregulated whenever intracellular PO2 dropped below ~10 mmHg." (PMID 28149279, 2016). "Vascular endothelial growth factor (VEGF) and hypoxia-inducible factor-1α (HIF-1α) are important for tumor growth and angiogenesis, which can be regulated by AKT signaling pathway." (PMID 27845405, 2016). "Tumor hypoxia prolongs HIF-1α activity, and induces VEGF expression, leading to promote angiogenesis and malignant tumor growth." (PMID 26822586, 2016). "Tumor development usually involves a hypoxic state sensed by the mTOR pathway leading to an activation of the hypoxia-inducible factor 1 alpha (HIF1A) to facilitate angiogenesis upon VEGFA induction." (PMID 27090655, 2016). "In these studies, cell-permeable iron was able to counteract the effect of Dynamin-2 inhibition on HIF-1α in tumor cells." (PMID 27589831, 2016). "There are elements in the tumor microenvironment such as TGFβ that influence the activity of HIF-1α under normoxia." (PMID 26905733, 2016). "In fact, both HIF1α and NFκB are induced by ROS and, in turn, can regulate ROS production to sustain tumor cell survival and growth." (PMID 26798421, 2016). "One important consequence of HIF-1α activation is the induction of glycolytic phenotype in tumor cells." (PMID 27458427, 2016). "In a variety of tumors, HIF-1α is overexpressed and modulates tumor cell growth, metastasis, and angiogenesis." (PMID 26784107, 2016). "HIF-1α inhibition in combination with antiangiogenic therapy is a promising strategy for targeting tumor resistance." (PMID 26933802, 2016). "In the present study, treatment with endostatin was found to suppress formation of new vasculature, decrease levels of VEGF and increase HIF1-α expression in tumors, thus aggravating hypoxia in the tumor microenvironment." (PMID 27703219, 2016).